TCFL5 (transcription factor like 5)
Description:
Putative transcription factor. Isoform 3 may play a role in early spermatogenesis.
Synonyms: E2BP-1; CHA; Figlb; bHLHe82; SOSF1
Tractability: PROTAC: ubiquitination databases record sites on it.
Gene: Protein-coding gene on chromosome 20 (62,841,005 to 62,861,825, reverse strand). Ensembl gene ENSG00000101190.
Subcellular location: Nucleus
Subcellular location (Human Protein Atlas): Nucleoplasm
Gene Ontology:
Molecular function: DNA binding; DNA-binding transcription repressor activity, RNA polymerase II-specific; RNA polymerase II cis-regulatory region sequence-specific DNA binding; sequence-specific double-stranded DNA binding; DNA-binding transcription factor activity; DNA-binding transcription factor activity, RNA polymerase II-specific; protein dimerization activity
Biological process: negative regulation of transcription by RNA polymerase II; regulation of cell differentiation; regulation of cell population proliferation; regulation of DNA-templated transcription; spermatogenesis; transcription by RNA polymerase II
Cellular component: nucleoplasm; nucleus; chromatin; male germ cell nucleus
Genetic constraint (gnomAD): Loss-of-function variants: 9 observed, 41.18 expected, observed/expected ratio (o/e) 0.22, 90% interval 0.13 to 0.38. The synonymous counts are far from expectation, so gnomAD's model fits this gene poorly and the ratio says little. Missense variants: 587 observed, 505.28 expected, observed/expected ratio (o/e) 1.16, 90% interval 1.09 to 1.24. Synonymous variants: 311 observed, 225.97 expected, observed/expected ratio (o/e) 1.38, 90% interval 1.25 to 1.51.
Homologues: Orthologues: macaque TCFL5 (97% identical), rat Tcfl5 (88% identical), mouse Tcfl5 (87% identical), pig TCFL5 (83% identical), dog TCFL5 (83% identical), chimpanzee TCFL5 (70% identical), guinea pig TCFL5 (54% identical).
Diseases named in the same sentence as TCFL5 in open-access papers:
TCFL5 is named in the same sentence as 23 diseases in open-access papers, as found by Europe PMC text mining. Sharing a sentence is not in itself a finding about the gene and the disease. The quoted sentences say what the papers report.
esophageal cancer (2 papers, 2022 to 2024). A primary or metastatic malignant neoplasm involving the esophagus. "CircRNA TCFL5 promotes esophageal cancer cell proliferation, invasion, and migration by regulating the FMNL2/miR-543 axis, mediates macrophage M2 polarization, and promotes tumor growth in vivo." (PMID 38523627, 2024). "Further analysis indicated that overexpressing circRNA TCFL5 promoted esophageal cancer progression both in vitro and in vivo." (PMID 35646112, 2022). "Xenograft tumors in nude mice were established to confirm the function of circRNA TCFL5 promoting esophageal cancer progression in vivo." (PMID 35646112, 2022). "In the present study, 156 upregulated circRNAs and 91 downregulated circRNAs were identified, and circRNA TCFL5 showed the most upregulated in esophageal cancer tissues compared with the control group." (PMID 35646112, 2022). "It is the first report that clarifies the function of circRNA TCFL5 in esophageal cancer progression." (PMID 35646112, 2022). "Taken together, we demonstrated that circRNA TCFL5 promotes esophageal cancer progression by modulating M2 macrophage polarization via the miR-543-FMNL2 axis." (PMID 35646112, 2022). "Of them, the expression of circRNA TCFL5 showed the most upregulated in esophageal cancer tissues compared with the control group." (PMID 35646112, 2022). "Mechanically, we demonstrated that circRNA TCFL5 promotes esophageal cancer progression by modulating M2 macrophage polarization via the miR-543-FMNL2 axis." (PMID 35646112, 2022). "We found that the expression of circRNA TCFL5 was significantly increased in esophageal cancer according to circRNA sequencing results, indicating that circRNA TCFL5 might promote esophageal cancer progression." (PMID 35646112, 2022). "In conclusion, we identified that circRNA TCFL5 was dramatically upregulated in esophageal cancer and could promote esophageal cancer progression both in vitro and in vivo." (PMID 35646112, 2022). "The function of circRNA TCFL5 on esophageal cancer progression was investigated." (PMID 35646112, 2022). "qRT-PCR analysis showed that the expression of circRNA TCFL5 was dramatically upregulated in the tumor group compared with the control group, suggesting that circRNA TCFL5 might promote esophageal cancer progression." (PMID 35646112, 2022). "Therefore, this study intends to explore the function of circRNA TCFL5 on esophageal cancer progression and whether M2 macrophages are involved." (PMID 35646112, 2022). "However, the function of miR-543 on esophageal cancer cells could be partially reversed by circRNA TCFL5." (PMID 35646112, 2022). "However, how circRNA TCFL5 affects the progression of esophageal cancer and whether it controls M2 macrophages remain unknown." (PMID 35646112, 2022).
infertile (2 papers, 2022 to 2024). "In contrast to our results, it has been recently described that TCFL5+/− mice were infertile due to abnormal spermatids, and thus those authors were unable to generate, TCFL5−/− knock out mice." (PMID 35768632, 2022). "The complete TCFL5 null mice model, using Sox2 promoter-controlled CRE recombinase, led to infertility in male mice." (PMID 35768632, 2022).
leukemia (2 papers, 2020 to 2021). A malignant (clonal) hematologic disorder, involving hematopoietic stem cells and characterized by the presence of primitive or atypical myeloid or lymphoid cells in the bone marrow and the blood. "Previous studies have identified various genes including EPOR, TCFL5, and TERF2 to be specifically overexpressed in ETV6-RUNX1 leukemia." (PMID 33708624, 2021). "TCFL5 has been previously shown to be upregulated in E/R+ pre-B-ALL, while GATA2 has been reported to contribute to the upregulation of erythroid genes, such as EPOR, a known marker gene in E/R+ leukemia." (PMID 33218352, 2020).
adenoma (1 paper, 2022). A neoplasm arising from the epithelium. "TCFL5 mRNA levels are higher in carcinomas than in adenomas, but this has been related to a 20q chromosomal amplification frequent in CRC." (PMID 34623757, 2022). "In CRC, TCFL5 expression has been found to be higher in carcinomas than in adenomas, likely due to amplification in chromosome 20q." (PMID 34623757, 2022).
Azoospermia (1 paper, 2022). Absence of any measurable level of sperm,whereby spermatozoa cannot be observed even after centrifugation of the semen pellet. "TCFL5 knockout results in azoospermia due to an arrest in the first meiotic prophase at the diplotene stage and conditional TCFL5-Tx results in the generation of abnormal spermatids." (PMID 35768632, 2022).
Chagas disease (1 paper, 2018). A parasitic infection caused by Trypanosoma cruzi. "Given that we saw more than twice as much Tcfl5 mRNA expression in the stellate ganglia of male mice, it would be interesting to know if the inflammatory state of the stellate ganglia is different between the sexes in Chagas’ Disease." (PMID 29895973, 2018).
colorectal cancer (1 paper, 2022). A primary or metastatic malignant neoplasm that affects the colon or rectum. "In this study, the authors identify four isoforms of TCFL5 in colorectal cancer, each with strikingly different properties." (PMID 34623757, 2022).
male infertility (1 paper, 2022). The inability of the male to effect fertilization of an ovum after a specified period of unprotected intercourse. "In agreement with this repressive role of TCFL5, a comprehensive functional enrichment analysis of male infertility, both in mouse models and in humans has found increased levels of Tcfl558." (PMID 35768632, 2022).
tumor (11 papers, 2017 to 2025). "This possibility fits with the fact that TCFL5 isoforms are significantly more expressed in patient’s tumours that also have those genes mutated than in those with PTEN or PI3KCA mutations." (PMID 34623757, 2022). "Complete deletion of the TCFL5 locus reduced tumour cell proliferation and spheroid formation, but increased migration." (PMID 34623757, 2022). "TCFL5 was significantly upregulated in carcinoma tissue being higher in advanced tumour stages, mostly in tumours that present metastasis in 1–3 lymph nodes and distant metastasis." (PMID 34623757, 2022). "Further analysis indicated that the tumor volume was remarkably higher with circRNA TCFL5 overexpression and lower with circRNA TCFL5 suppression than in the NC group." (PMID 35646112, 2022). "Thus, knocking down the TCFL5 locus drastically reduced HCT116 tumour growth ability in vivo, proving its relevant role in this process." (PMID 34623757, 2022). "In this regard, we observed that TCFL5 negatively regulates SOX2 in human tumor cells." (PMID 35768632, 2022). "Thus, the deletion of the complete knockout of TCFL5 in these cell lines may lead to some deleterious DNA alterations that will require the tumour suppressor activity to maintain cell viability." (PMID 34623757, 2022). "Detailed analysis of TCFL5 isoforms in RNAseq from CRC data set showed that CHA, TCFL5_E6 and TCFL5_E7 were all detectable in human CRC tumours." (PMID 34623757, 2022). "Overexpression of circRNA TCFL5 promotes proliferation, invasion, and migration of Eca109 and KYSE150 and promotes tumor growth in vivo." (PMID 35646112, 2022). "The most striking effect was observed in vivo while studying the tumorigenic capacity of these cells: CHA overexpression did not affect while TCFL5_E8 overexpression drastically reduced the tumour growth of HCT116 xenografts." (PMID 34623757, 2022). "Moreover, in HT29 colon carcinoma cell line induction of TCFL5 during multicellular tumour spheroids (MCTS) formation, an in vitro cellular aggregation model which mimics tumour formation has been described." (PMID 34623757, 2022). "Moreover, we compared the expression of each TCFL5 exon with that of SOX2 and KLF4 in tumour samples." (PMID 34623757, 2022). "However, we demonstrated here that TCFL5 locus might give rise to four different transcripts in CRC cell lines and tumours with different relative expression." (PMID 34623757, 2022). "However, our analysis of the available databases indicates that a significant percentage (40%) of CRC tumours had some kind of alteration in TCFL5 but in the great majority not resulting from amplification, nor mutation rather from an increase in mRNA levels." (PMID 34623757, 2022). "Positive correlation of TCFL5 and SOX2 was found in the normal region adjacent to the tumour samples but not in healthy tissue or tumour samples, while KLF4 negatively correlated with TCFL5 in tumour samples." (PMID 34623757, 2022).
cancer (3 papers, 2017 to 2022). A tumor composed of atypical neoplastic, often pleomorphic cells that invade other tissues. "This work also points to the need to analyse separately TCFL5 isoforms in cancer, due to their different and opposite functions." (PMID 34623757, 2022). "IGF1R, one of the members of the insulin/IGF system, was mostly expressed in foetal and cancer tissues 39 and three CpG islands are predicted in the promoter region of IGF1R which may combine large list of transcript factors including MZF1, TCFL5, USF1, ETS1 and SPIB." (PMID 33085184, 2020).
TCFL5 also shares sentences with these, for which no sentence is quoted: influenza (14 papers); infection (5); Viral Infection (3); acute coronary syndrome (1); atherosclerosis (1); cardiovascular disease (1); colitis (1); demyelinating disorders (1); epilepsy (1); neurodegenerative disease (1); pancreatic cancer (1); tendinopathy (1); upper respiratory tract infection (1).